NR2F6 (nuclear receptor subfamily 2 group F member 6)
Diseases named in the same sentence as NR2F6 in open-access papers (continued):
Sharing a sentence is not in itself a finding about the gene and the disease.
tumor (continued). "Our results suggest that NR2F6 plays a crucial role in tumor-promoting effects and can be used as a potential prognostic marker for NB." (PMID 40424451, 2025). "NR2F6 (Ear-2) is an orphan nuclear receptor with varying expression levels in different standard and tumor tissues." (PMID 40424451, 2025). "Any rational drug design targeting NR2F6-mediated gene regulation would have critical clinical applications by affecting both tumor-abnormal effector T cells and tumor cells while inducing tumor cell death." (PMID 40424451, 2025). "In the inflammatory tumor microenvironment, NR2F6 is highly inducible in effector T cells, locally activating T-cell immunity and reducing immune-related adverse effects." (PMID 40424451, 2025). "NR2F6 is an orphan nuclear factor that functions as a tumor promoting protein in both tumor and immune cells." (PMID 39128718, 2024). "Specifically, circRHOT1 promotes HCC cell growth, invasion, and tumor formation via recruiting the chromatin remodeling factor TIP60 to the NR2F6 (Nuclear Receptor Subfamily 2 Group F Member 6) promoter, thus triggering its transcription." (PMID 38398157, 2024). "The intrinsic and extrinsic roles of NR2F6 in tumours justify its consideration in the development of effective anticancer therapies." (PMID 39169517, 2024). "It is interesting to note that while exogenous expression of NR2F6 following circMIRO1 depletion in HCC xenograft models fully rescued tumor growth, exogenous expression of c-MYC had only a partial rescue of tumor growth in NSCLC xenograft models." (PMID 39128718, 2024). "Our findings establish a tumor-intrinsic function for NR2F6 and identify NACC1 and FKBP10 as their downstream effectors in inhibiting antitumor immunity." (PMID 37406115, 2023). "Our analysis of the tumor-infiltrating immune cells showed that NR2F6 was related to immunosuppressive cells such as regulatory T cells (Tregs), macrophages, and neutrophils." (PMID 37575237, 2023). "Some authors suggest that an overexpression of NR2F6 reduces the cytokine production and promotes tumor growth this way." (PMID 36884115, 2023). "Specifically, NR2F6 has recently gained attention as a therapeutic target boosting anti-tumour immunotherapy response." (PMID 37370765, 2023). "Next, we used RNA-seq to assess transcriptomic changes in the presence of NR2F6 KO and WT tumor cells." (PMID 37406115, 2023). "Of nine genes down-regulated by NR2F6 loss, NACC1 and FKBP10 were negatively correlated with the IFN-γ signature, while high NACC1 and FKBP10 expression was associated with poor overall survival, patterns seen upon tumor-intrinsic NR2F6 inactivation." (PMID 37406115, 2023). "In agreement, NR2F6 KO mice inoculated with NR2F6 KO tumor cells exhibited prolonged survival compared with NR2F6 WT mice inoculated with NR2F6 KO tumor cells or NR2F6 KO mice inoculated with NR2F6 WT tumor cells." (PMID 37406115, 2023). "Previous studies of graft models using subcutaneous injection of NR2F6-expressing WT tumor cells suggest that NR2F6 regulates immune system activities independently of its tumor cell expression." (PMID 37406115, 2023). "To further assess the effects of tumor-intrinsic NR2F6 expression on antitumor immunity, we monitored the infiltration ofmelanoma tumors by tumor-infiltrating lymphocytes (TILs) inthe presence or absence of tumor-intrinsic NR2F6expression." (PMID 37406115, 2023). "Accordingly, a genetic mouse model with global NR2F6 ablation exhibits accelerated inflammation, autoimmune phenotypes, and attenuated tumor growth due to enhanced activity of tumor-infiltrating effector T cells." (PMID 37406115, 2023). "Previous studies have demonstrated that NR2F6 plays a dual function in immune cells and in tumor cells." (PMID 37575237, 2023).
tumor (continued). "Tumor-intrinsic NR2F6 function complements its tumor-extrinsic role and justifies the development of effective anticancer therapies." (PMID 37406115, 2023). "Here, we add an important component to this equation by demonstrating that tumor-intrinsic NR2F6 expression is equally relevant and that combining tumor-intrinsic and -extrinsic NR2F6 ablation synergizes to block tumor growth." (PMID 37406115, 2023). "The accumulated siRNA blocks intracellular immune checkpoint NR2F6 to promote an immunogenic TME that allows powerful anti-tumor T-cell responses." (PMID 35907841, 2022). "The accumulated siRNA suppressed the signal of dual protumor activity in both immune and H22 tumor cells by silencing the NR2F6 gene, which further reduced the tumor burden and enhanced systemic antitumor immunity." (PMID 35907841, 2022). "Our pH-sensitive CCF nanoparticles are responsive to the slightly acidic tumor extracellular environment to improve tumor accumulation and cellular uptake efficiency and effectively deliver Nr2f6 siRNA into H22 tumor cells and T cells to degrade mRNA." (PMID 35907841, 2022). "The re-exposed hexagonal CCF-LDHs loaded with Nr2f6 siRNA were efficiently internalized and triggered Nr2f6 siRNA release to down-regulate NR2F6 expression in both immune and H22 cells, which blocked its dual pro-tumor activity." (PMID 35907841, 2022). "To reveal the role of NR2F6 in residual tumor, we selected the overlaps that were both upregulated in residual tumor and targeted by NR2F6, and we eventually figured out 150 promising genes regulated by NR2F6 in residual tumor." (PMID 34304715, 2021). "This compartmentalization at the tumor site, per definition, decreases the chances of systemic side effects and thus should enable more precise therapy for patients during the envisioned NR2F6-targeted therapy regimen." (PMID 34073258, 2021). "Blocking NR2F6 thus can boost an anti-tumor immune response through direct transcriptional de-repression of key cytokine loci (e.g., Il2, Ifng in the T cell effector compartment)." (PMID 34073258, 2021). "We finally selected 150 novel target genes of NR2F6 in residual tumor of incomplete ablation, and these genes appeared to be associated with the biological regulation of lipid metabolism-related pathway." (PMID 34304715, 2021). "Nevertheless, it cannot be argued based simply on these reports that decreased NR2F6 protein levels in these individuals will also elicit enhanced anti-tumor immunity." (PMID 34073258, 2021). "Performing experiments to identify ligands for the LBD of NR2F6 from tumor tissue, lipid species that co-immunoprecipitated with NR2F were detected using liquid chromatography coupled to mass spectrometry (LC-MS)." (PMID 34073258, 2021). "The potential druggability of its LBD for a “small-molecule checkpoint blockade drug” therefore very likely offers a rational mechanistic basis for the targeted manipulation of NR2F6 in tumor-infiltrating T cells." (PMID 34073258, 2021). "Heterozygous Nr2f6+/− mice similarly showed a strong benefit in terms of tumor growth suppression, demonstrating haploinsufficiency." (PMID 34073258, 2021). "Remarkably, beside its role in immune cells, NR2F6 expression also appears important in tumor cells, correlating with a faster tumor growth and worse patient overall survival outcomes." (PMID 34073258, 2021). "Current preclinical experimental knowledge firmly validates the immune checkpoint function of NR2F6 in murine tumor models, which provides a promising perspective for immunotherapy regimens in humans in the near future." (PMID 34073258, 2021). "Not only is the site of origin related to the NR2F6 expression, but so is the immune status of a tumor." (PMID 32752295, 2020). "Pursuing this concept, and mirroring in principle a pharmacological treatment, therapeutic adoptive transfer (ACT) of acute Nr2f6 gene-edited autologous CD3+ T cells into tumor-bearing mice in a combinatorial CTLA-4 or PD-L1 blockade setting was carried out." (PMID 31937317, 2020).
tumor (continued). "As a remarkable result, 66.67% or 8 out of 12 mice receiving CD3CRISPR.Nr2f6 with αCTLA-4 and 37.5% (3/8) with αPD-L1 therapy survived the tumor burden." (PMID 31937317, 2020). "At the individual gene level, the nuclear orphan receptor NR2F6 together with the transcription factor ATF2 emerged as the most significant mutually exclusive gene pair in pan-tumor analysis." (PMID 32117236, 2020). "In HCC, circRHOT1 is significantly up‐regulated and initiate NR2F6 expression to promote tumour progression, the expression of circRHOT1 was related to patient prognosis." (PMID 32697386, 2020). "Despite the differences in the overall NR2F6 expression at the different tumor sites, NR2F6 seems to be upregulated in the PTs with an LR, independently of the mean expression level at the tumor site." (PMID 32752295, 2020). "Gottfried Baier (Innsbruck, Austria) presented another new target for tumor immunotherapy, namely, the orphan nuclear receptor NR2F6." (PMID 32025850, 2020). "RNA sequencing (RNAseq) analysis of TILs derived from wild-type and Nr2f6−/− tumor-bearing mice collected at d14 after B16-OVA tumor cell injection clearly demonstrated that the NR2F6- and PD-1-mediated immune-suppressive pathways are mechanistically distinct." (PMID 29670099, 2018). "Genetic ablation of Nr2f6, particularly in combination with established cancer immune checkpoint blockade, efficiently delays tumor progression and improves survival in experimental mouse models." (PMID 29670099, 2018). "It was thus mandatory to further investigate the network of critical target genes suppressed and/or activated by Nr2f6 gene induction within the tumor microenvironment (TME)." (PMID 29670099, 2018). "Comparable to the Nr2f6−/− mice, tumor progression was also significantly slower and overall tumor masses smaller in heterozygous Nr2f6+/− mice." (PMID 29670099, 2018). "Taken together, genetic NR2F6 ablation acts as a “sensitizer” that allows improved therapeutic activity of the clinically approved PD-1/PD-L1 axis blockade in experimental mouse tumor model systems." (PMID 29670099, 2018). "Along this line of argumentation, intriguingly, even heterozygous Nr2f6+/− mice exhibited the same ability to delay tumor outgrowth of implanted B16-OVA and MC38 tumors as Nr2f6 knockout mice." (PMID 29670099, 2018). "Adoptively transferred Nr2f6 silenced CD3+ T cells therefore act as robust “sensitizer” for the established anti-PD-L1 immune checkpoint blockade in mouse tumor models in vivo." (PMID 29670099, 2018). "According to all our preclinical data, high NR2F6 expression is likely to critically contribute to the immune-suppressed state of tumor antigen-specific TILs, thus limiting the host’s anti-tumor immune response." (PMID 29670099, 2018). "In our cohort, there was a strong correlation between NR2F6 protein expression and tumor recurrence." (PMID 27775588, 2016). "This raises the question of whether nuclear membrane migration of NR2F6 is indicative of tumor progression or related to the cell differentiation mechanism, necessitating further experimental exploration." (PMID 40424451, 2025). "Moreover, NR2F6 plays a unique role in the tumor immune microenvironment, affecting the immune infiltration within the tumor." (PMID 40424451, 2025). "The therapeutic targeting of NR2F6 may be a promising strategy for boosting NKp46-dependent NK-cell-mediated tumor surveillance and metastasis." (PMID 39920136, 2025). "NR2F6 might be a critical immune checkpoint in the T-cell compartment, controlling tumor progression and growth." (PMID 40424451, 2025). "Thus, the relationship between the level of NR2F6 expression in pancancer and immune infiltration and tumor prognosis deserves further investigation." (PMID 40424451, 2025). "NR2F6 is a transcription factor that can influence the tumor microenvironment in various ways." (PMID 40424451, 2025).
tumor (continued). "In addition, we examined the NR2F6 expression level in NB tumor samples from our hospital and divided them into two groups of high and low expression." (PMID 40424451, 2025). "In vitro studies have shown that NR2F6 is an inhibitory receptor in tumor-associated non-regulatory T cells, highly expressed on so-called “exhausted” T cells to reactivate tumor-specific T lymphocytes." (PMID 40424451, 2025). "NR2F6 (nuclear receptor subfamily 2F group member 6, also known as Ear-2) is an orphan nuclear receptor with dual pro-tumorigenic activity in the immune system and tumor cells." (PMID 40424451, 2025). "The nuclear receptor (NR) NR2F6 was identified as a regulator of anti‐tumour immunity." (PMID 39169517, 2024). "NR2F6 is an orphan nuclear receptor involved in the regulation of T cells and anti-tumor immunity." (PMID 38829910, 2024). "In addition, analysis of NR2F6 regulated process during emergency granulopoiesis in infection or tumor models will be of interest in future studies." (PMID 39840064, 2024). "Previous studies have suggested that Nr2f6 may positively regulate tumour cell survival and induce cancer progression." (PMID 36927450, 2023). "In vitro studies revealed NR2F6 acting as inhibitory receptor, highly expressed on so called “exhausted” T cells, as they might be found in tumor tissue due to a tumor-related unregulated T-cell activation process." (PMID 36884115, 2023). "Given that NR2F6 is a transcriptional factor, it may influence the microenvironment of a tumor in multiple ways." (PMID 36884115, 2023). "However, the tumor-intrinsic function of NR2F6 in shaping an antitumor immune response in the tumor niche remains largely unexplored." (PMID 37406115, 2023). "Our analysis found that NR2F6 was positively related to M2 differentiation factors, suggesting that it may contribute to a tumor microenvironment favorable for tumor growth through promoting the M2-polarization of tumor-associated macrophages." (PMID 37575237, 2023). "It was previously demonstrated that tumor-extrinsic NR2F6 expression could block antitumor immunity in genetically ablated NR2F6 KO mice." (PMID 37406115, 2023). "To determine whether candidate NR2F6 effectors exhibit antitumor activity, we asked whether NACC1 and/or FKBP10 loss would phenocopy NR2F6 loss and attenuate tumor growth." (PMID 37406115, 2023). "We identify a tumor-intrinsic function of the orphan NR, NR2F6, regulating antitumor immunity." (PMID 37406115, 2023). "The NR2F6 expression level increased with increasing tumor grade." (PMID 37575237, 2023). "As expected, NR2F6 lossreduced tumor volume and weight compared with NR2F6 WT controls." (PMID 37406115, 2023). "Based on the dual protumor activity of NR2F6 in both immune and tumor cells, inhibition of NR2F6 may exert a unique and beneficial effect on HCC, realizing two birds with one stone." (PMID 35907841, 2022). "In NSCLC tissues, high expression of NR2F6 was detected in tumor-infiltrating lymphocytes (TILs), and upregulated NR2F6 expression was associated with impaired production of cytokines, including IL-2, TNF-α, and IFN-γ,185 suggesting that NR2F6 on TILs contributes to tumor immunosuppression." (PMID 36123348, 2022). "Furthermore, NR2F6 downregulation sensitizes tumors to established PD-1/PD-L1 axis blockade to prevent tumor progression due to the positive correlation between NR2F6 expression and the T-cell dysfunction/exhaustion phenotype." (PMID 35907841, 2022). "However, Nr2f6 also has a critical role in lymphocyte differentiation and T-cell mediated tumor surveillance, suggesting requirements in mesodermally-derived tissues and neofunctionalization in adaptive immunity." (PMID 34807940, 2021). "The aim of this paper is to investigate the role of NR2F6 in the progression of residual tumor." (PMID 34304715, 2021).
tumor (continued). "Of note, the overexpression of NR2F6 was also detected in residual tumor (log2FC = 1.590, p = 0.03), suggesting that NR2F6 might also play an important role in residual tumor." (PMID 34304715, 2021). "Furthermore, analyzing TILs in human NSCLC biopsy samples provides strong preclinical evidence that the upregulation of NR2F6 at the tumor site produces effector T cells incapable of achieving an adequate immune response against cancer." (PMID 34073258, 2021). "Subsequently, a higher NR2F6 was also detected in residual tumor following insufficient ablation." (PMID 34304715, 2021). "NR2F6 was defined as an intracellular immune checkpoint in tumor-infiltrating T-cells." (PMID 32752295, 2020). "Despite its activating ligand is unknown, the receptor is essential for transcription and NR2F6 k.o. mice display autoimmunity and high rejection of transplantable tumor." (PMID 32025850, 2020). "It has previously been shown that Nr2f6−/− T cells are hyper-reactive in regard of cytokine production (IL-2, IFNγ, TNFα) as those cytokines are direct target genes of NR2F6-dependent transcriptional repression leading to an improved anti-tumor immune contexture at the tumor site." (PMID 31937317, 2020). "Additionally, as a therapeutic approach, we previously have demonstrated that adoptively transferred Nr2f6 siRNA-silenced polyclonal CD3+ T cells act as an adjuvant for the established αPD-L1 immune checkpoint in the mouse B16-OVA tumor model." (PMID 31937317, 2020). "Taken together, CRISPR/Cas9-mediated acute Nr2f6 gene ablation in primary mouse T cells prior to ACT appeared feasible for potentiating established PD-L1 and CTLA-4 blockade therapies, thereby pioneering NR2F6 inhibition as a sensitizing target for augmented tumor regression." (PMID 31937317, 2020). "Notably, our preclinical proof of concept study on the acute and CRISPR/Cas9-mediated Nr2f6 gene depletion acts as a robust “sensitizer” for established immune checkpoint blockade in the mouse MC38 tumor model." (PMID 31937317, 2020). "For clinical diagnostics, it might be necessary to define particular thresholds for the assessment of the NR2F6 expression for every HNSCC tumor site." (PMID 32752295, 2020). "We further analyzed whether the NR2F6 expression still correlated with the occurrence of an LR, depending on the tumor sites (pharynx, larynx, and oral cavity)." (PMID 32752295, 2020). "In vivo xenograft experiments showed that knockout of circRHOT1 or NR2F6 suppressed tumor growth." (PMID 31324186, 2019). "Similarly, the treatment of MC38 tumor-bearing heterozygous Nr2f6+/− mice with αPD-L1 is as effective as in knockout mice." (PMID 29670099, 2018). "This provides strong preclinical evidence that NR2F6 and PD-1 signaling may act together as “threshold regulators” in host-protective tumor immunity." (PMID 29670099, 2018). "Significant higher NR2F6 mRNA expression could also be seen in sorted CD3+ T cells of tumor tissue from NSCLC patients compared to PBMCs." (PMID 29670099, 2018). "Another immune cell type in which NR2F6 has been shown to play an important role is the macrophage, which may suppress immune cell genes in reverse transcriptional activation in human macrophages to promote tumor development." (PMID 40424451, 2025). "NR2F6 (nuclear receptor subfamily 2 group F member 6, also called Ear-2) is known to be an orphan nuclear receptor that has been characterized as an intracellular immune checkpoint in effector T cells and, therefore, may control tumor development and growth." (PMID 36884115, 2023). "Furthermore, NR2F6 seems to modulate anti-inflammatory signals between T cells, which may ameliorate the individual anti-tumor response." (PMID 36884115, 2023). "Moreover, the disruption of NR2F6 resulted in tumor suppression and enhanced the effect of PD-L1 blockade in tumor therapy, suggesting that NR2F6 inhibitors may become a new type of immunotherapy that can overcome resistance to existing ICB treatment." (PMID 36123348, 2022).